CD4 (CD4 molecule)
Diseases named in the same sentence as CD4 in open-access papers (continued):
Sharing a sentence is not in itself a finding about the gene and the disease.
tumor (continued). "Moreover, consistent with the fact that IFN-γ+ cells, CD4+, and CD8+ T cells are not affected by neutrophil depletion in vivo, we found that neutrophils from tumor-bearing mice preferentially impacted the in vitro proliferation of CD27− γδ T cells when compared to CD27+ γδ, CD4+, and CD8+ T cells." (PMID 29750788, 2018). "Interestingly, in their models of prostate cancer, CD4+ T-cell-derived TGF-β (conventional and Tregs) was relevant to the prevention of spontaneous tumor formation, while conventional T-cell TGF-β production impeded the immune-mediated restriction of tumor growth and metastasis." (PMID 29891791, 2018). "Interestingly, TIL cultures established from tumour biopsies of different anatomical sites from the same patient often showed variable CD4+:CD8+ T-cell ratios although no consistent pattern was seen." (PMID 30039427, 2018). "Moreover, the appearance of clustered CD4+ and CD19+ B cells in the stroma surrounding the tumor region suggests the emergence of ectopic lymphoid structures (ELSs) during HCC development in this model, similar to the findings in human HCC specimens and other HCC mouse models." (PMID 30526672, 2018). "CD4+ T cells in the general or tumor compartment had no influence on OS, RFS or DSS." (PMID 29872507, 2018). "Although not well characterized, CD4+ Th cells have been shown to inhibit tumour growth." (PMID 28944998, 2018). "Interestingly, the anti-CD4 mAb treatment-induced expansion of overlapping clones occurred mainly in the dLN rather than in the tumor." (PMID 30733724, 2018). "Comparing control tumor-bearing mice without treatment, sunitinib administration led to the slight reduction in the frequency of CD4+ T cells from 68% to 67%, but small increase of CD4+ T cells seen in sorafenib-treated mice from 68% to 70%." (PMID 30123861, 2018). "CD8 but not CD4 T cells depletion in mice treated with miRNA mimics diminished the inhibitory effect of miRNA mimics on metastasis and primary tumor weight." (PMID 29973593, 2018). "The most predictive feature derived from the non-tumor compartment is the fraction of Ki67 single-positive markers at most 15 μm from the closest non-proliferating either CD4 or CD8 marker, i.e., the same feature as in (a) but evaluated in the non-tumor compartment." (PMID 30619761, 2018). "Therefore, using dual staining and co-localization of markers such as CD4 and Foxp3 could clarify the role of Treg TIL subset in the tumor microenvironment more accurately." (PMID 30460193, 2018). "Using CD4 and CD8 T cell-deficient mice, Lee and coworkers showed that Salmonella treatment of Lewis lung carcinoma (LL2)-bearing mice was relatively less efficient in the absence of T cells (34–42% inhibition in tumor growth compared to 50% in WT mice)." (PMID 29765907, 2018). "CD4+ and CD8+ T cells are the primary effectors against several different tumors, and their increase in the peripheral blood and spleen may reflect an immunostimulatory and an enhancement of their bioavailability in the tumor site." (PMID 30079021, 2018). "Importantly, these tumor growth effects depend primarily on NR2F6 function in both CD4+ and CD8+ effector (but not regulatory) T-cell subsets." (PMID 29670099, 2018). "Moreover, the tumor-infiltrating lymphocyte (TIL) investigation indicated that nivolumab increased CD4+ and CD8+ lymphocytes in the lung but not in the primary lesion." (PMID 29409495, 2018). "CD4 T-cells activated by direct recognition of HLA class II molecules during immunization may act as providers of T-helper activity, triggering and sustaining a TAA-specific immune response against the patient’s own tumor cells." (PMID 30150597, 2018). "Therefore, we characterized CD4 and CD8 populations in the spleen and tumor site." (PMID 30006573, 2018).
tumor (continued). "We also found that patients with advanced-stage tumors had less CD4 and CD8, lower CD4/FOPX3 and CD8/FOXP3 ratios, and higher CD3/CD4 and CD3/CD8 ratios, which may suggest that as their tumors progressed, the tumor microenvironment shifted toward a more immunosuppressive environment." (PMID 30153850, 2018). "As expected, no CD4+ T-cells were detected in the tumor of anti-CD4-treated mice." (PMID 29348598, 2018). "The immune-inflamed phenotype is characterized by the presence of both CD4+ and CD8+ T cells, often accompanied by myeloid and monocytic cells, and by staining for Programmed Death Ligand (PDL)-1 on tumor-infiltrating lymphocytes (TILs) and, in some cases, on tumor cells." (PMID 30477280, 2018). "Thus, either CD4+ T cell unresponsiveness is not due to a lack of inflammatory signal or tumor-related signals are dominant over the effect of CpG." (PMID 29844317, 2018). "Besides FOXP3+CD4+ Treg cells, other immune cell types, such as NK cells, immunoregulatory APCs, MDSCs, and CD8+ regulatory cells, may affect tumor progression and directly or indirectly enhance T cell dysfunction." (PMID 28545567, 2017). "A separate study also demonstrated that adoptive transfer of NKG2D-based CAR T cells could recruit and activate endogenous antigen-specific CD4+ and CD8+ T cells at the tumor site in a CXCR3-dependent manner to achieve optimal eradication of ID8 ovarian cancer." (PMID 29312333, 2017). "Upon treatment with NY-ESO-1, a widely used tumor antigen for vaccination, and imiquimod, CD4+T cell responses but not CD8+T cell responses could be observed in melanoma patients." (PMID 28620298, 2017). "However, absence of CD4+/CD8+ T cells had no measurable inhibitory effect on induction of tumor apoptosis, nor did it inhibit macrophage efflux or influx of NK cells." (PMID 29195074, 2017). "Notably, all mice receiving combined anti-CD4/anti-PD-1 mAb immunotherapy initially developed disseminated tumors, similarly to control mice, as evaluated by luciferase-based IVIS on day 15 after tumor challenge." (PMID 29070883, 2017). "However, whether DC vaccines could defeat the immune suppressive tumor microenvironment and efficiently activate and expand tumor-specific CD8+ and CD4+ T cells, which could further eliminate tumor cells, remained questionable." (PMID 28330473, 2017). "Wu.S2013, et.al reported that Aidi injection with chemotherapy could significantly improve the percentage of CD3+T cells, CD4+T cells, CD8+T cells and NK cells and the CD4+/CD8+ T cells ratio in peripheral blood, and improve tumor immunity of patient with NSCLC." (PMID 27901493, 2017). "Thus, once the E7-specific CD8+ T cell response has been generated, the CD4+ T cells do not appear to be necessary for the subsequent protection of tumor formation." (PMID 28852471, 2017). "To evaluate the potential role of Tregs and its subsets in human GC, we first gated CD4+CD25+Foxp3+ T lymphocytes as Tregs and analyzed the Treg percentage within the total CD4+ T-cell populations from peripheral blood, non-tumor, peritumoral, and tumor tissues of GC patients." (PMID 28817117, 2017). "Although the absence of PD-L1 expression from either tumour or host cells produced similar increases in CD4 and CD8 T cell infiltration, but discrete transcriptional profiles, it was of interest to determine if there were other differences in tumour immune regulation." (PMID 28220772, 2017). "Similarly, the percentages of CD4+ CD25− conventional T-cell subset in the spleen were significantly increased on day 21 and 28 after the treatment (P<0.01 compared with the control group on day 26 after tumor inoculation), along with a higher IFN-γ level." (PMID 28333145, 2017). "By contrast, both CD4 and FoxP3 staining were primarily restricted to the stromal regions of tumor sections taken from patients with CRC regardless of whether they received enadenotucirev by IT injection or IV infusion." (PMID 28923104, 2017).
tumor (continued). "Researches have demonstrated that CD4+ CD25+ Foxp3+ Tregs inhibited proliferation, activation, degranulation, and production of granzyme A, granzyme B, and perforin of CD8+ T cells induced by anti-CD3/CD28 antibodies and are potent suppressors of autologous tumor-specific T cell responses." (PMID 28399886, 2017). "In the present study, we first conducted a ‘tumor microenvironment PCR Array’ of ccRCC samples of different Fuhrman grades and found that myofibroblast-like cells (indicated by the presence of α-SMA) and CD4+ T cells were increased in Fuhrman III–IV ccRCC samples." (PMID 28846080, 2017). "Depletion of NRP1 in CD4+ T cells resulted in breakdown of tumor induced tolerance and activated antitumor immune response in tumor bearing mice, evident from increased CD8+ and reduced Treg cell infiltration into the TME, lesser tumor burden and improved tumor free survival." (PMID 29067024, 2017). "Furthermore, it has been shown that both CD4+ and CD8+ effector T lymphocytes may have anti-tumor properties and independently correlate with improved outcome." (PMID 29020986, 2017). "Because of its structure, the secreted scFv can link tumor cells with T-cells by acting as a bridge to activate intrinsic TCR/CD3 complex of BiTEs, but it is unknown whether CD4 or CD8 molecules of T-cells participate in this process because of the lack of MHC expression on tumor cells." (PMID 29312360, 2017). "In summary, our findings explore the generation and functions of tumor-induced CD8+ Treg cells that suppress the anti-tumor immunity alone or synergistically with CD4+ Treg cells indicating that targeting only CD4+ Treg is not sufficient to circumvent tumor immune evasion." (PMID 28487507, 2017). "In the present study, we found that elevated CD4+ naïve/memory ratio was independently associated with prolonged PFS in NSCLC patients; elevated peripheral memory CD4+ cells may indicate poor survival, which is contrary to the role of CD45RO+ tumor-infiltrating lymphocytes in tumor tissues." (PMID 29137371, 2017). "In addition, the therapeutic outcomes in M3-9-M tumor models correlated with the increased incidence of CD4+ and CD8+ T cells but not with the CD4+CD25+Foxp3+ regulatory T cell populations in the tumor." (PMID 28539588, 2017). "Moreover, these antimalarial drugs failed to affect spontaneous tumor infiltration by CD3+CD4+ and CD3+CD8+ T cells and the activation/exhaustion status of these cells [55 Apetoh, 2015, 26137416]." (PMID 27974686, 2017). "Now, in this scenario, it was noticeable that in tumor milieu, both CD4+ and CD8+ Treg cells are equipped with immunosuppressive properties which compelled us to check whether both of these T-regulatory cells work together to ensure tumor immune escape." (PMID 28487507, 2017). "Moreover, the total number of CD8+ T cells but not CD4+ T cells was increased in the tumours of Grail−/− mice inoculated with EL-4 tumour cells compared to WT mice." (PMID 28798332, 2017). "In addition, MSI-H tumor cells have been shown to generate and present novel tumor-specific frameshift-derived neopeptides (FPS); these appear to affect the immune responses mediated by neoepitope-specific CD4+ T cells." (PMID 28488173, 2017). "Alternatively, a population of regulatory CD4 T cells that are CD25- (thus not depleted by aCD25) could play a role in this tumor model." (PMID 29312597, 2017). "Although the percentage of CD25+FoxP3+ regulatory T cells among CD4+ T cells in the spleen of Her2/CT26 tumor-bearing mice was not changed significantly by the administration of TSA, TSA treatment significantly reduced the number of CD25+FoxP3+ Treg cells compared to vehicle treatment." (PMID 28489607, 2017). "Normally, CD4+ T cells predominates among LN leukocytes in the naive mouse; however, B cells became the most prominent population proportionally within TDLN 3 days after tumor injections, and the trend continued until after day 7 when the relative composition returned to baseline." (PMID 29109732, 2017).
tumor (continued). "qPCR revealed that the triple treatment resulted in the highest expression of mRNA for the T cell specific chemokines CXCL9 and CXCL10 in tumors, suggesting that these two chemokines might be responsible for the enhanced infiltration of CD4+ and CD8+ T cells in the tumor tissues after treatment." (PMID 28881713, 2017). "Our observation that PD-1hiICOSint and PD-1intICOShi CD4+ TIL are linearly correlated in 90% of BC, suggests that effector Th plus TfhX13 TIL frequently expand in parallel with activated Treg TIL, thereby generating anti-tumor immunity and memory that is regulated by immune feedback mechanisms." (PMID 29163490, 2017). "Interestingly, IL-17RB was selectively expressed by intra-tumor CD4+ T cells, but not CD8+ T, NK, γδ T cells or macrophages." (PMID 27909985, 2017). "CD4+CD45RA+CD45RO+ cells transitioned from naïve to memory cells after stimulation by tumor antigen; increased proportions of these cells may suggest higher tumor malignancy and invasion." (PMID 29137371, 2017). "Moreover, we identified two MPM effusion-related factors with clinical value: CD4+ T cells were significantly correlated with better response to chemotherapy, while the percentage of PD-L1+ podoplanin (PDPN)+ tumor cells is a significant prognostic factor for worse outcome." (PMID 29163783, 2017). "Most importantly, depletion of CD4+ T cells did not abolish the tumor‐promoting effect of activin." (PMID 27932444, 2017). "Similarly, a significant number of tumor infiltrating CD4+ve and CD8+ve lymphocytes express PD-1, suggesting that inhibition of PD-1 might be a good strategy in this tumor." (PMID 29069740, 2017). "Alternatively, the facts that antitumor CTL rely on IL-2 and IFNγ for tumor rejection and that pancreatic HNT CD4+ T cells were able here to secrete IFNγ and IL-2 in response to antigen suggest that these cytokines may be involved in providing help to clone 4 CD8+ T cells." (PMID 29403481, 2017). "Hence, also CD4+ T cell depletion does not guarantee a more pronounced expansion of tumor-specific CD8+ T cells." (PMID 28401257, 2017). "In addition, APS inhibit the tumor cell growth in Kunming mice with Ehrlich's ascites carcinoma, decrease Bcl-2 and CDK4 levels, increase the percentage of CD3+ and CD4+ T-lymphocytes, the ratio of CD4+/CD8+ T cells and the expression of IL-2/IL-2R in spleen and Bax in tumor tissue." (PMID 29344421, 2017). "These tumor-infiltrating B cells acquired PD-L1 expression and TGF-β competency which contributed to an immunosuppressive phenotype characterized by an enhanced inhibitory capacity against CD4+CD25− T cells, CD8+ T cells, and CD49b+NK cells, as well as promotion of Treg expansion." (PMID 28261223, 2017). "Since we previously found that the expansion of tumor-specific T cells became visible after 2 weeks of culture, our data suggested that the presence of high numbers of CD4+CD25hiFoxP3+ T cells at this time point had a negative impact on overall T cell proliferation." (PMID 28401257, 2017). "Removal of CD4+T cells or CD8+T cells significantly weakened the antitumor effect of in vivo R428 treatment, indicating that R428 may engage the immune effectors to inhibit tumor growth in vivo." (PMID 29163786, 2017). "In addition, we could find that the number of Treg cells expressing CD4, CD25, and FoxP3 were decreased in tumor tissue by TSA treatment." (PMID 28489607, 2017). "Taken together these results support the hypothesis that CD4+ T cells play an immunoregulatory tumor-promoting role in mice with EMT6 tumors, while CD8+ cells play a protective role in attenuating tumor growth-and that CD200 expression by tumor cells further modulates these effects." (PMID 28234914, 2017). "Furthermore, tumor-specific CD4+ and CD8+ IFN-γ secreting cells could be efficiently expanded from mice immunized with EVs A, showing that a T helper 1 response is involved in tumor rejection." (PMID 28360912, 2017).
tumor (continued). "to explore a protective role for CD8+T cells in the anti-EMT6 tumor immune response, and assess a contrary role for CD4+Tregs, by characterizing the TILs and DLN cells in WT mice challenged with EMT6 and EMT6siCD200 tumors and treated with CD8 and CD4 depleting antibodies." (PMID 28234914, 2017). "Although our therapy did not potentiate the frequency of endogenous CD4+ T cells or NK cells in the peripheral blood, it remains unknown if this regimen induced immune response in the tumor microenvironment." (PMID 28388966, 2017). "This enhanced tumor immunity suggests that helper function may not be the only way CD4+ T cells contribute to the TSC tumor immunity." (PMID 28428886, 2017). "Moreover, Cbx3/HP1γ insufficiency did not affect the generation of natural CD4+ Treg cells in tumor bearing mice." (PMID 28220815, 2017). "Tumor-infiltrated CD4+ T-cell levels were not significantly different between treatment groups." (PMID 28537894, 2017). "Based on our results showing IRF8 overexpression in the DLBCL tumor microenvironment and previous findings showing that IRF8 inhibits Th17 differentiation in CD4+T cells in mice, we investigated whether IRF8 affected the generation of Th17 cells in the tumor microenvironment in vitro." (PMID 28537908, 2017). "Although CD4+CD25hiFoxP3+ T cell depletion strategies turned out not to be robust enough to allow implementation into a clinical protocol aiming at improved generation of tumor-reactive T cells, inhibition of IDO and galectin-3 proved to be successful." (PMID 28401257, 2017). "Similar as before the reduced frequency of CD4+ Tregs in B16SLC35A1 tumors was concomitant with increased IFN-γ production by infiltrating lymphocytes, indicating a shift from T cell tolerance towards T cell immunity that sets stage early after tumor implantation." (PMID 26741508, 2016). "We hypothesize that MHC-II expression is either (i) a functional antigen-presenting molecule that can promote CD4 T-helper cell aid to the anti-tumour milieu or (ii) a non-functional marker of the inflammatory state of the cell or tumour milieu." (PMID 26822383, 2016). "Previous studies have showed that metronomic dosing of TMZ can reduce the ratio of Treg/CD4+ cells whereas higher doses do not, and this reduction in Tregs could potentially reverse immunosuppression within the tumor microenvironment." (PMID 27876012, 2016). "However, MHC-II expression on the tumour did correlate with CD4 infiltrate, though the nature or composition of these CD4+ cells is not yet understood (Th1, Th2, Th17 or Tregs)." (PMID 26822383, 2016). "In addition, there were more CD4+ T-cells in Py117 compared with Py8119 tumours that did not change after radiation." (PMID 28008921, 2016). "We found that delivering LPS after the ACT regimen increased the absolute number of donor CD8+ T cells to host CD4+ T cells in the spleen of irradiated mice 7 days after the treatment regimen, which likely explains why this approach effectively regresses B16F10 tumor." (PMID 26885368, 2016). "Moreover, immunofluorescence analysis in tumor tissue treated with the combined vaccine was extensively infiltrated with higher numbers of CD4+ and CD8+T immune cells compared with the control, especially CD4+ T cells." (PMID 29263903, 2016). "Therefore, although differences in ICOS expression on CD4+ T cells were observed, they were not alone characteristic of protective anti-tumor immune responses." (PMID 26961085, 2016). "Hence, neither the priming nor the effector phase of the CD4+ T cell response was affected by the absence of tumor cell-intrinsic MHC II display." (PMID 27626487, 2016). "Bregs may support expansion of suppressive Tregs and MDSCs, suppress stimulatory Th1/Th17 cells, promote skewing of T-helper cells and macrophages toward suppressive Th2/M2 types, and/or may interact directly with effector CD4+ and CD8+ T cell and/or NK cells to suppress anti-tumor immunity." (PMID 27437104, 2016).